FGFR1 (fibroblast growth factor receptor 1)
Diseases named in the same sentence as FGFR1 in open-access papers (continued):
Sharing a sentence is not in itself a finding about the gene and the disease.
pancreatic cancer (continued). "FGFR1 expression, as estimated by IHC, may be used to define clinically distinct subtypes in pancreatic cancer." (PMID 30593273, 2018). "The clinical significance of fibroblast growth factor receptor 1 (FGFR1) protein expression in pancreatic cancer is largely unknown." (PMID 30593273, 2018). "Nevertheless, the clinical significance of FGFR1 protein expression in pancreatic cancer is still largely unknown." (PMID 30593273, 2018). "Another reason contributing to the down-regulation of SPARC in human pancreatic cancer cells may be the over-expression of FGFR1-IIIc." (PMID 19920824, 2010). "Therefore, assessing the FGFR1/2 expression profile in each pancreatic tumor could significantly contribute to predicting tumor cell response to paracrine factors and therapies." (PMID 38339360, 2024). "Moreover, FGFR1-based subclassification of pancreatic cancer may lead to new therapeutic approaches for the FGFR1-positive subtype." (PMID 30593273, 2018). "Moreover, FGFR1 overexpression may define a subset of pancreatic cancer, leading to new therapeutic approaches." (PMID 30593273, 2018). "In another report of pancreatic cancer, CERS6-AS1 sequesters miR-15a-5p, which induces the expression of FGFR1 and HMGA1, two key oncogenes, promoting pancreatic cancer proliferation and migration." (PMID 35927226, 2022). "We also tested BGJ398 sensitivity in 3 pancreatic cancer PDOs, including 1 (HO219) with a FGFR1-ERLIN2 chromosomal fusion, and observed increased sensitivity to BGJ398 in HO219 compared with 2 FGFR–wild-type PDAC PDOs." (PMID 36256477, 2022). "Here, we reported, for the first time, that combined treatment with FGFR1 and PLK1 inhibitors evokes synergistic cytotoxic activity in KRAS‐mutant lung and pancreatic cancer models in vitro and in vivo." (PMID 34369083, 2021). "Similar to FGFR1, PARP1 mRNA expression (ILMN_1686871) was approximately 1.81-fold (p < 0.01) higher in dasatinib-resistant pancreatic cancer cells than in dasatinib-sensitive cells (lower)." (PMID 32276472, 2020). "We then examined the expression of FGFR1 and FGFR2 by western blot and showed that FGFR1 and FGFR2 are widely expressed throughout these pancreatic cancer cell lines." (PMID 32457900, 2020). "The FGFR1 IIIb induced cell proliferation after FGF‐1, FGF‐2 and FGF‐4 stimulations via production of a glycosylated 110kd protein in pancreatic cancer cells." (PMID 30945363, 2019). "Another study using an organotypic model of PDAC showed that nuclear translocation of fibroblast growth factor 2 (FGF2) and fibroblast growth factor receptor 1 (FGFR1) in PSCs drives invasion of both PSCs and pancreatic cancer cells into the surrounding ECM." (PMID 29903049, 2018). "In pancreatic cancer, aberrations in the FGFR pathway, particularly FGFR1 overexpression, have been reported." (PMID 30593273, 2018). "We demonstrated that miR-497 plays a role in modulating the malignant phenotype and chemosensitivity of pancreatic cancer cells by directly inhibition of FGF2 and FGFR1 expression." (PMID 25149530, 2014). "The set of matching genes downregulated in pancreatic cancer contains MLH1 as a predicted target for miR-155, and FGFR1 as a target of miR-10." (PMID 21738581, 2011). "Interestingly, the nuclear translocation of FGFR1 and FGF2 in pancreatic stellate cells favors pancreatic cancer cell invasion." (PMID 37750089, 2023). "Furthermore, multivariate analysis also revealed FGFR1 and FGF14 as independent prognostic markers for better overall survival in pancreatic cancer patients." (PMID 34061869, 2021). "In this context, a recent research work describes the important role of oncogenic K-ras, growth factor receptors (FGFR1 and EGFR) and ROS in regulating PD-L1 expression in pancreatic cancer cells and aids significant new mechanistic insights in this important area." (PMID 34503236, 2021).
pancreatic cancer (continued). "Pancreatic carcinoma genes are involved in various apoptotic processes and significantly connected on both protein and pathway levels, highlighting the BAX and survivin protein complexes, and FGFR1, SCF-KIT, and PGDF signaling pathways, respectively." (PMID 34753928, 2021). "In addition, we also showed that FGFR1 and FGFR2 are key receptors in regulating pancreatic cancer stemness." (PMID 32457900, 2020). "On the other hand, a recent study performed in the Korean patients showed that FGFR1 positive pancreatic cancer had better overall survival as compared to FGFR1 negative pancreatic cancer, which is consistent with the findings of our study." (PMID 32171280, 2020). "Lehnen and colleagues observed that 4% (5/125) of pancreatic cancer patients showed FGFR1 expression, and amplification was noted in 2.6% of the cases (4/155)." (PMID 30593273, 2018). "In pancreatic cancer, FGFR1 is the most frequently altered receptor of the four FGFR receptors, and, using readily applicable immunohistochemistry methods, FGFR1 can be used to classify pancreatic cancer into FGFR1-positive and -negative subtypes." (PMID 30593273, 2018). "The FGFR1 inhibitor PD173074 also decreased PD-L1 protein levels, but not mRNA levels, in in vitro and in vivo mouse pancreatic tumor models." (PMID 34503236, 2021). "At the invasive front of human pancreatic cancer, FGF2 and FGFR1 localise to the nucleus in activated PSCs but not cancer cells." (PMID 24503018, 2014).
squamous cell carcinoma (38 papers, 2012 to 2025). A carcinoma arising from squamous epithelial cells. "FGFR1 is reported to be prognostic biomarker in squamous cell carcinoma and the abnormalities of FGFR1 has been shown to be associated with several cancer types including AML." (PMID 27564113, 2017). "FGFR2, FGFR3, and FGFR4 expression were elevated in squamous cell carcinoma, and a high expression of FGFR1, FGFR2, FGFR3, and FGFR4 were associated with a less aggressive phenotype." (PMID 27154171, 2016). "Although the amplification of FGFR1 is reportedly predominant in squamous cell carcinomas, the association with overexpression was inconclusive." (PMID 25989941, 2015). "In NSCLC, up to 50% in adenocarcinomas of Asian patients harbor activating mutations of EGFR, and approximately 20% of squamous cell carcinomas have fibroblast growth factor receptor 1 (FGFR1) amplifications." (PMID 24816813, 2014). "In squamous cell carcinoma, FGFR1 amplification is found to be associated with poor outcomes." (PMID 39796710, 2024). "It is possible that the rate of FGFR1 amplification is related to smoking history, specifically prolonged smoking, which may account for the perceived association with squamous cell carcinoma, since it is this subtype that is most closely associated with cigarette consumption." (PMID 24255716, 2013). "FGFR1 amplification is a recurrent alteration in NSCLC, particularly in squamous carcinoma, and confers oncogenic dependency targetable by FGFR1 inhibitors." (PMID 41303594, 2025). "Squamous-cell carcinoma (SCC) is distinguished by somatic mutations in genes such as SOX2, platelet-derived growth factor receptor A (PDGFR-A), fibroblast growth factor receptor 1 (FGFR1), and discoidin domain receptor tyrosine kinase 2 (DDR2)." (PMID 40429689, 2025). "Of note, squamous cell carcinoma cases had enrichment of fusions involving FGFR1 (0.9% vs 0.3%), FGFR3 (0.8% vs 0.2%), and PIK3CA (0.5% vs <0.01%)." (PMID 39664186, 2024). "Approximately 20% of squamous cell carcinomas and 3–5% of adenocarcinomas have FGFR1 amplification, while about 1–3% of NSCLC cases have FGFR2 and FGFR3 fusions." (PMID 39796710, 2024). "The predicted positive ratios of FGFR1-4 were generally over 10% in most tumor types, especially in squamous cell carcinoma." (PMID 32596330, 2020). "The purpose of this study was to evaluate PD-L1, FGFR1, PIK3CA, PTEN, and p16 expression in squamous cell carcinoma (SCC) associated with emphysema/COPD." (PMID 31481045, 2019). "Fibroblast growth factor receptor 1 (FGFR1) has been noted to be amplified in a variety of squamous cell carcinomas (SCCa) of the head, neck, and lung and increased copy number (CN) is a predictor of poor outcomes." (PMID 29351293, 2018). "In BM of NSCLC, fibroblast growth factor receptor 1 (FGFR1) amplifications are found in 19% of squamous cell carcinomas, and in 15% of adenocarcinomas." (PMID 29881714, 2018). "While FGFR1 amplifications have been found in up to 22% of squamous cell carcinomas of the lung and about 15% in head and neck cancers, we found neither FGFR1, FGFR2, nor FGFR3 amplifications by FISH in squamous differentiated bladder cancer." (PMID 27669755, 2016). "We found a striking predominance of FGFR1 amplification in squamous cell cancers (8.9%) as compared to adenocarcinomas (1.6%) in our study on 510 esophageal cancers." (PMID 26555375, 2015). "FGFR1 amplification, defined as a ratio of FGFR1:centromere 8 copy numbers ≥ 2.0, was more frequently seen in squamous cell carcinoma (8.9% of 202 interpretable cases) than in adenocarcinoma (1.6% of 308; p<0.0001)." (PMID 26555375, 2015). "Our data demonstrate marked differences in the prevalence of FGFR1 gene amplification between squamous cell carcinomas and adenocarcinomas of esophageal carcinomas." (PMID 26555375, 2015). "Lymph node metastases derived from FGFR1-amplified squamous cell cancer also are known to exhibit FGFR1 amplification." (PMID 23936763, 2013).
squamous cell carcinoma (continued). "Recently, amplification of the fibroblast growth factor receptor 1 (FGFR1) gene has been described as an oncogenic alteration in a subgroup of squamous cell carcinomas." (PMID 24255716, 2013). "The safety and tolerability of AZD4547 (AstraZeneca, London, UK) in FGFR1 and/or FGFR2 gene amplified solid tumors and FGFR1 gene amplified squamous cell cancer is being studied in an ongoing study." (PMID 23936763, 2013). "Focal amplification of the Fibroblast Growth Factor Receptor 1 (FGFR1) gene has recently been identified in up to 20% of squamous cell carcinomas." (PMID 25562798, 2012). "Additionally, specific subtypes are characterized by different mutations: adenocarcinoma typically exhibits changes in the EGFR and ALK genes, while squamous cell carcinoma is associated with alterations in the PIK3CA and FGFR1 genes." (PMID 38339175, 2024). "Also, different subtypes also had their own specific variants, such as MET in adenocarcinoma, FGFR1 and FGFR3 in squamous cell carcinoma and MYC in small cell lung cancer." (PMID 31616594, 2019). "This study was designed to investigate the prevalence and clinical significance of FGFR1 amplification in a tissue microarray containing 346 adenocarcinomas and 254 squamous cell carcinomas of the esophagus, using dual-labeling fluorescence in situ hybridization (FISH) analysis." (PMID 26555375, 2015). "In conclusion, FGFR1 amplification occurs in a relevant subgroup of carcinomas of the esophagus and may play a particular role for development of squamous cell cancers." (PMID 26555375, 2015). "Reported FGFR1 amplification frequencies in studies on 32–189 esophageal cancers range between 6–21% in squamous cell cancers and 9% in adenocarcinomas, but the impact on patient prognosis is largely unknown." (PMID 26555375, 2015). "Although our results showed that functional FGFR1 signaling is not significantly changed in our lung adenocarcinoma cell system, FGFR1 suppression by miR-133a is detected in the reporter assay, and miR-133a-suppressed FGFR1 mRNA levels have been detected in four squamous cell carcinomas." (PMID 24816813, 2014). "Interestingly, The Cancer Genome Atlas Research (TCGA) network recently reported a comprehensive analysis of genomic and epigenomic alterations in 178 squamous cell carcinomas of the lung and found that the rate of FGFR1 amplification was 7%." (PMID 24255716, 2013). "Using this cutpoint, the rate of FGFR1 amplified tumors was 5.1% in squamous cell carcinomas." (PMID 24255716, 2013). "In addition, multiplex testing for driver mutations in 72 squamous cell carcinomas of the lung detected: PIK3CA mutations in 8%, PTEN mutation/deletion in 28%, FGFR1 amplification in 26%, and unknown genetic alterations in 39%." (PMID 25348872, 2014). "For example, it was shown that PD 173074, FGFR1 inhibitor, reversed ABCB1-mediated multidrug resistance to colchicine (CH), paclitaxel (PTX), and vinblastine (Vin) in CH-resistant human epidermoid carcinoma cell subline and ABCB1-overexpressing HEK293 cells." (PMID 35327403, 2022). "Targeting of FGFR1 was found to increase radiation-induced killing of mesothelioma cells, whereas inhibition of FGFR3 enhanced radiosensitivity of squamous cell carcinomas." (PMID 31948066, 2020). "FGFR1 was more highly expressed in adeno-/adenosquamous carcinoma, while FGFR2, FGFR3, and FGFR4 expression was more prominent in squamous cell carcinoma (P = 0.020, P < 0.001, P < 0.001, and P = 0.020, respectively)." (PMID 27154171, 2016).
squamous cell carcinoma (continued). "FGFR1 was highly expressed in adeno-/adenosquamous carcinoma (P = 0.020), while FGFR2, FGFR3, and FGFR4 expression were more prominent in squamous cell carcinoma (P < 0.001, P < 0.001, and P = 0.020, respectively)." (PMID 27154171, 2016). "In NSCLC patients, FGFR1 amplifications regulates cell proliferation through activation of the MAPK and PI3K/AKT pathways in about 20% of squamous cell carcinomas but they are rarely detected in adenocarcinomas." (PMID 24816813, 2014). "In another study, these authors demonstrated that fibroblast growth factor receptor 1 (FGFR1) amplification in brain metastases of adenocarcinomas – but not squamous cell carcinomas, is fivefold more frequent than reported for primary tumors (~3%)." (PMID 29868480, 2018). "FGFR1 amplification was unrelated to tumor stage, grade, lymph node metastasis and clinical outcome in the 202 esophagus squamous cell carcinomas analyzed in this study." (PMID 26555375, 2015). "Indeed, Chen Z-S with colleagues demonstrated that PD 173074, FGFR1 inhibitor, reversed ABCB1-mediated multidrug resistance to colchicine, PTX, and vinblastine (Vin) in colchicine-resistant human epidermoid carcinoma cell subline and ABCB1-overexpressing HEK293 cells, as well." (PMID 35327403, 2022). "However, their genomic profiling lacked diverse genetic alterations characterized in squamous cell carcinoma, such as SOX2 amplification in the squamous differentiation pathway; PIK3CA amplification in the PI3K signaling; and FGFR1 amplification in the RTK signaling pathway." (PMID 32726920, 2020). "Therefore, although FGFR1 mediated regulation has not been detected in CL1-5 and A549 cells, it may be an important factor in miR-133a-mediated tumor suppression in squamous cell carcinoma tumorigenesis." (PMID 24816813, 2014).
osteosarcoma (37 papers, 2011 to 2025). A usually aggressive malignant bone-forming mesenchymal neoplasm, predominantly affecting adolescents and young adults. "This suggests that FGFR1 amplification is associated with poor response of osteosarcoma to chemotherapy." (PMID 32984034, 2020). "FGFR1 amplification in human osteosarcoma is associated with worse response to chemotherapy." (PMID 30890123, 2019). "Furthermore, FGFR1 is highly expressed in osteosarcoma and is associated with poor prognosis." (PMID 37361567, 2023). "The FGFR1 gene is often amplified in osteosarcoma cell lines and silencing of its expression has been shown to reduce proliferation in osteosarcoma-derived cells." (PMID 40806483, 2025). "Similar to findings in osteosarcoma, FGFR1 is over- expressed in the majority of the osteosarcoma tissue samples, and it is associated with a high incidence of metastasis and poor prognosis." (PMID 37361567, 2023). "In paediatric cancers, FGFR amplification is rare but predominately identified in sarcomas, particularly osteosarcoma (OS), and less frequently in brain tumours, with gain of FGFR1 being most common." (PMID 37130917, 2023). "Sulfatinib targets FGFR1, which is highly expressed in osteosarcoma and is a bFGF- binding receptor." (PMID 37361567, 2023). "While pre-clinical data is limited, one study demonstrated that FGFR1 amplification in 1/17 primary osteosarcoma samples predicted sensitivity to the selective FGFR-inhibitor NVP-BGJ398." (PMID 37130917, 2023). "In this study, we found that sulfatinib inhibits the phosphorylation of FGFR1, and downstream kinases in osteosarcoma cells play key roles in the inhibition of proliferation, promoting apoptosis and enhancing chemo-sensitivity." (PMID 37361567, 2023). "To verify the results obtained for NLS mutants, we also knocked-down LRRC59, a protein-mediating nuclear transport of FGF1, in the human osteosarcoma U2OSR1 cell line constitutively expressing FGFR1." (PMID 35159330, 2022). "Evaluation of the targeting effect of PCI of FGF-SAP was done by comparing the cytotoxic response in osteosarcoma cells with very low levels of FGFR1 (U2OS) to cells overexpressing FGFR1 (U2OS-R1)." (PMID 34204611, 2021). "Sequencing revealed a persisting H3F3A mutation in the osteosarcoma while the pleomorphic sarcoma lost the H3F3A mutation; however, a FGFR1 mutation, both in the recurrence and in the pleomorphic sarcoma persisted." (PMID 33707617, 2021). "More recently, a novel interaction was identified between FGFR1 and galectin-1 (LGALS1)/galectin-3 (LGALS3) in osteosarcoma cells ectopically expressing FGFR1." (PMID 34068954, 2021). "Another study, which included 352 osteosarcoma samples, detected FGFR1 amplification in 18% of the chemotherapy resistant osteosarcoma patients." (PMID 32984034, 2020). "We confirmed these findings using another model cell line, human osteosarcoma U2OS cells that stably expresses FGFR1 (U2OS-R1)." (PMID 31013829, 2019). "Osteosarcomas were significantly enriched for a cluster of six skeletal-pathway kinases that includes FGFR1 and FGFR2." (PMID 30890123, 2019). "Here, we demonstrate that in NIH3T3 mouse fibroblasts and human osteosarcoma U2OS cells stably expressing FGFR1, in addition to Erk1 and Erk2, p38 kinase is able to phosphorylate FRS2." (PMID 31013829, 2019). "Our results indicate that developed scFvs and scFvs-Fc reduce the in vitro proliferation of FGFR1-expressing mouse fibroblast NIH/3T3cells, FGFR1-transfected BaF3 cells, and most importantly G-292 human osteosarcoma cancer cells." (PMID 30134556, 2018).